MUSK (muscle associated receptor tyrosine kinase)
Diseases named in the same sentence as MUSK in open-access papers (continued):
Sharing a sentence is not in itself a finding about the gene and the disease.
thymoma (continued). "In contrast, the presence of MuSK antibodies in the thymoma-MG subgroup is extremely rare, and it is presumed that thymus is not involved in the pathogenesis of MuSK-MG." (PMID 25915571, 2015). "Ocular myasthenia with MuSK antibodies or thymoma is extremely uncommon." (PMID 39105625, 2024). "Presence of thymoma, signs of NMT failure in limb muscles on electrophysiological testing, detection of AChR and MuSK Abs, and increased serum levels of microRNA miR-30e-5p were found to be associated with increased risk of secondary generalization." (PMID 33329368, 2020). "In adult non-thymoma AChRAb negative patients, 15 patients were MuSK antibody positive and 69 patients were MuSK antibody negative." (PMID 33633666, 2021). "It is presumed that thymus is not related to the pathogenesis of MG in MG patients with MuSK antibodies, and extremely rare MuSK antibodies are found in MG patients with thymoma." (PMID 31915455, 2019). "Three MG patients presented with significant bulbar palsy symptoms, high AChR-Ab titers, and negative MuSK-Ab, were diagnosed with thymoma." (PMID 29670572, 2018). "This concept is also supported by the observation that MG patients with MuSK antibodies patients do not appear to have thymic hyperplasia or thymoma." (PMID 24632822, 2014). "Thymus changes are not a common feature of MuSK positive disease, and thymoma has not been reported in MuSK-positive children." (PMID 22110902, 2011). "AChR and MuSK Ab detection by radioimmunoassay (RIA) is highly specific, as AChR Abs are rarely found in subjects with other diseases or thymoma without MG, and MuSK Abs have never been reported in non-MG patients." (PMID 33329368, 2020). "In one case, AChR, MuSK and VGKC antibodies co-occurred with MG and Morvan's syndrome without any thymoma." (PMID 25915571, 2015).
congenital myasthenic syndrome (31 papers, 2011 to 2026). Congenital myasthenic syndrome (CMS) is a group of genetic disorders of impaired neuromuscular transmission at the motor endplate characterized by fatigable muscle weakness. "The patient exhibited mutations in DOK7 (downstream of kinase), an adapter protein for MuSK, which is an important cause of congenital myasthenia." (PMID 37303354, 2023). "Mutations in LRP4 or MuSK and autoantibodies directed against these proteins cause congenital myasthenic syndromes and myasthenia gravis, respectively." (PMID 37356721, 2023). "Mutations in MUSK are responsible for an autosomal recessive form of congenital myasthenic syndrome and a recessive form of fetal akinesia deformation sequence (FADS), providing support for its involvement in fetal development." (PMID 33937227, 2021). "We report a patient with severe early‐onset congenital myasthenic syndrome and two novel missense mutations in the muscle‐specific receptor tyrosine kinase (MUSK; p.C317R and p.A617V)." (PMID 31765060, 2020). "We report a patient with severe early‐onset congenital myasthenic syndrome and two novel missense mutations in MUSK (p.C317R and p.A617V)." (PMID 31765060, 2020). "A variant of rapsyn, a muscle nAChR chaperone that concentrates and anchors muscle nAChR in the postsynaptic membrane of the neuromuscular junction, causes congenital myasthenic syndrome by altering interactions with the receptor muscle specific tyrosine kinase (MuSK)." (PMID 38472514, 2024). "This hypothesis is supported by experiments analyzing MuSK mutations identified in patients with congenital myasthenic syndromes." (PMID 39703505, 2024). "Mutations in MUSK have been associated with congenital myasthenic syndromes." (PMID 39650478, 2024). "Our case further supports that laryngeal stridor, vocal cord paralysis, and feeding difficulties could be the early diagnostic clues of a congenital myasthenic syndrome with neonatal onset due to a mutation in the MUSK gene." (PMID 37240968, 2023). "Mutations in the MuSK gene may cause congenital myasthenic syndromes (CMS), a type of hereditary disease characterized by muscles that fatigue easily resulting in muscle weakness caused by neuromuscular transmission dysfunction in humans." (PMID 21383979, 2011). "In the study of congenital myasthenic syndrome due to MuSK mutation, the changes in the presynaptic morphology were assumed to reflect a disturbance in muscle-derived retrograde signals resulting from the impairment of agrin- and Dok7-induced MuSK phosphorylation." (PMID 32547365, 2020). "Components of the LRP4/MuSK/Dok-7 complex are the targets of mutations responsible for subsets of congenital myasthenic syndromes (CMS), which are characterized by fatigable muscle weakness." (PMID 29462491, 2018). "The β-adrenergic agonists salbutamol and ephedrine have been well established for the therapy of congenital myasthenic syndromes with AGRN, COLQ, DOK7, LRP4 and MUSK mutations, but with only anecdotal clinical experience of salbutamol in MuSK-MG." (PMID 39703505, 2024). "Mutations in MUSK and genes that act in the MuSK signaling system (including DOK7) induce congenital myasthenia." (PMID 37240968, 2023). "It is worth noting that gene mutations in the agrin-LRP4-MuSK-Dok7-rapsyn-AChR pathway, including the genes AGRN, MUSK, DOK7, RAPSN, cause congenital myasthenic syndromes (CMSs)." (PMID 33328881, 2020). "In common with the Dok-7 congenital myasthenia, anti-MuSK MG is thought to interfere with MuSK signaling in the postsynaptic membrane." (PMID 24505322, 2014). "Mutations in FZ-CRD of Frizzled class receptor 4 (FZD4) and Muscle, skeletal, receptor tyrosine kinase (MuSK) and Receptor tyrosine kinase-like orphan receptor 2 (ROR2) cause Familial Exudative Vitreoretinopathy (FEVR), Congenital Myasthenic Syndrome (CMS), and Robinow Syndrome (RS) respectively." (PMID 31892318, 2019).
congenital myasthenic syndrome (continued). "Consistent with this idea, adenoviral expression of Dok-7, an inside-outside activator of MuSK, not only extends longevity of SOD1-G93A mice but also provides benefit in other mouse models of neuromuscular disease, including congenital myasthenia and Emery-Dreifuss muscular dystrophy." (PMID 29460776, 2018). "Treatment-refractory ophthalmoparesis/plegia among particularly the prepubertal group of juveniles with AChR-Ab negative MG or MuSK-Ab negative MG, may raise the possibility of a congenital myasthenic syndrome (CMS)." (PMID 35280301, 2022).
autoimmune disease (24 papers, 2015 to 2025). A disorder resulting from loss of function or tissue destruction of an organ or multiple organs, arising from humoral or cellular immune responses of the individual to their own tissue constituents. "Rituximab was used as a first-line option in 4 patients (1.9%): 2 anti-MuSK-associated MG cases, 1 with comorbid autoimmune disease and 1 EOMG case with an aggressive course." (PMID 38529037, 2024). "From an analysis of coexisting antibodies, MG patients often have the presence of thyroid autoantibodies, while MuSK antibody-positive MG patients exhibit coexisting autoimmune diseases, predominantly Hashimoto thyroiditis and rheumatoid arthritis." (PMID 38405140, 2024). "MG is an autoimmune disease of the neuromuscular junction, which is mainly mediated by acetylcholine receptor (AChR) antibody and muscle-specific kinase (MuSK)." (PMID 35795289, 2022). "Once this group of MuSK-Ab-positive MG patients (MuSK-MG) was identified, clinical characteristics of MuSK-MG were discerned that distinguish it from AChR-MG, suggesting that MuSK-MG is a distinct autoimmune disease." (PMID 32457737, 2020). "MG is a B-cell mediated organ-specific autoimmune disease with antibodies against the acetylcholine receptor, muscle-specific kinase (MUSK), lipoprotein-related protein 4 (LRP4), or agrin in the post-synaptic membrane at the neuromuscular junction." (PMID 32982946, 2020). "In Japanese study, other autoimmune disorders occurred more often in seropositive MG patients (24.1%), than in MuSK‐Ab‐positive patients (8.4%) among which ATDs were predominant." (PMID 27781146, 2016). "MuSK-positive MG was rarely accompanied by autoimmune diseases because thymic abnormalities were not involved in the pathogenesis of MuSK-MG." (PMID 37781409, 2023). "Both had no history of autoimmune disease and no recent inflammatory events and were negative for serum MuSK autoantibodies." (PMID 31217355, 2019). "In the current study, we sought to expand cross-disease autoantibody exploration to include four validated neurologic autoantibodies (MOG, AQP4, AChR, and MuSK) in nonneurologic autoimmune diseases." (PMID 30824481, 2019).
Autoimmunity (9 papers, 2018 to 2024). The occurrence of an immune reaction against the organism's own cells or tissues. "Most of these observations have focused on AChR-MG, while there are few reports on poly autoimmunity in MuSK-MG patients." (PMID 37781409, 2023). "MuSK autoimmunity may differ in this regard in that only few clones—or even a single clone—could contribute to the production of circulating pathogenic autoantibody, and the expanded plasmablast compartment appears to include many specificities, few of which are MuSK-specific." (PMID 36307868, 2022). "MG with Abs to MuSK (MuSK-MG) was one of the first diseases in which IgG4 pathogenicity was demonstrated and currently represents a prototype of IgG4-mediated autoimmunity." (PMID 32431692, 2020). "Similarly, IgG4 autoantibodies in rheumatoid arthritis were found to be bispecific, and recently we were able to demonstrate the same for an example of IgG4 autoimmunity, as a large proportion of patient-derived MuSK autoantibodies were bispecific as well." (PMID 29483905, 2018). "In an experimental autoimmune MG mouse model, MuSK-CAART reduced anti-MuSK IgG but not B cell counts or total IgG levels, indicating that MuSK-specific B cell depletion occurred in treated mice." (PMID 38903526, 2024). "Screening cell-based immunofluorescence assays revealed a higher frequency of MOG and MuSK autoantibody-positive samples compared with AChR or AQP4 (a total of 12/643 [1.9%], 8/643 [1.2%], 5/643 [0.8%], and 4/643 [0.6%] positive samples in the nonneurologic autoimmunity cohorts, respectively)." (PMID 30824481, 2019).
sarcopenia (9 papers, 2013 to 2024). Progressive decline in muscle mass due to aging which results in decreased functional capacity of muscles. "Here we demonstrate that the agrin biologic NT-1654 is capable of activating the agrin/Lrp4/MuSK system in vivo, leading to an almost full reversal of the sarcopenia-like phenotype in neurotrypsin-overexpressing (SARCO) mice." (PMID 24520420, 2014). "Together, these results suggest that Yap signaling and α-DG, rather than MuSK signaling, are involved in the accelerated sarcopenia onset caused by Agrin deficiency." (PMID 38461287, 2024). "The MuSK-BMP pathway could also be a target for promoting muscle growth and treating conditions associated with muscle atrophy such as sarcopenia, immobilization, and cachexia." (PMID 38172960, 2024). "Moreover, the agrin partner MuSK also decreases during sarcopenia, further supporting a key role of agrin-MuSK pathway during aging." (PMID 33815879, 2021).
amyotrophic lateral sclerosis (7 papers, 2018 to 2024). Amyotrophic lateral sclerosis (ALS) is a neurodegenerative disease characterized by progressive muscular paralysis reflecting degeneration of motor neurons in the primary motor cortex, corticospinal tracts, brainstem and spinal cord. "The mechanisms by which boosting MuSK phosphorylation ameliorates pathology in mouse models of amyotrophic lateral sclerosis and spinal muscular atrophy are not well understood, as MuSK is neither mutated nor a direct target in these diseases." (PMID 39288173, 2024). "Interestingly, outside MG pathology, the promotion of MuSK activation constitutes a promising therapeutic strategy for other diseases such as amyotrophic lateral sclerosis (ALS)." (PMID 37564637, 2023). "Indeed, overexpression of a low copy number of MuSK partially rescues the NMJ degeneration that takes place at pre-symptomatic stages of Amyotrophic Lateral Sclerosis animal models (Pérez-Garcia and Burden, 2012)." (PMID 32848618, 2020). "The clinical phenotype of anti-MuSK+ MG may be different from anti-AChR+ forms, dominated by oculo-bulbar involvement, sometimes with amyotrophy and lingual fasciculations that may mimic amyotrophic lateral sclerosis with bulbar onset." (PMID 39555481, 2024). "In SOD1 G93A mice, a mouse model for amyotrophic lateral sclerosis (ALS), boosting retrograde signaling by modestly increasing MuSK gene expression decreases the rate and extent of denervation and improves motor performance." (PMID 29415504, 2018). "Thus, enhancing MuSK activity may mitigate NMJ defects in diseases of the NMJ, such as amyotrophic lateral sclerosis (ALS) and SMA." (PMID 34360794, 2021).
muscle atrophy (6 papers, 2013 to 2025). The loss of muscle tissue due to inactivity or disease. "Muscle atrophy in the face and tongue has been reported in patients with anti-muscle-specific kinase (anti-MuSK antibodies) in several studies which can cause prominent bulbar palsy compared with anti-AchR-positive MG." (PMID 34834491, 2021). "This suggests that the serum of MuSK-MG can influence the expression of proteins related to the development of muscle atrophy, with facial muscles being the most sensitive." (PMID 40356916, 2025). "Muscle atrophy in MG is not only seen in muscle-specific tyrosine kinase (MuSK)-MG but also in AChR-MG and seronegative MG." (PMID 40356916, 2025). "In vitro, anti-MuSK Ab induce inhibition of proliferation of a cell line, an effect correlated with disease severity and anti-MuSK Ab titer, that could explain the muscle atrophy in MuSK+ MG patients." (PMID 31920954, 2019). "Our previous case series found that muscle atrophy in MG is not exclusive to MuSK-MG but also occurs in AChR-MG and seronegative MG, with tongue muscle atrophy being the most common form." (PMID 40356916, 2025).
ptosis (6 papers, 2014 to 2025). The drooping of the upper eyelid. "CMS due to MUSK mutations is rare and manifests as respiratory insufficiency, neonatal ptosis, proximal limb muscle weakness, and weak bulbar, facial, or ocular muscles." (PMID 30808424, 2019). "In our cohort, the most common presenting symptoms were ptosis, diplopia, and generalized weakness in the AChR-Abs and triple-SN-MG-Abs groups and ptosis, diplopia, dysphagia, and dysphonia in the MuSK-Abs MG group." (PMID 38316426, 2024). "AChR-Ab and MuSK-Ab expression coexisted in patient 1 (a 50-year-old female who presented with ptosis at onset and had minimal manifestations at the last follow-up after a series of treatments)." (PMID 35246057, 2022).
respiratory failure (4 papers, 2013 to 2023). The significant impairment of gas exchange within the lungs resulting in hypoxia, hypercarbia, or both, to the extent that organ tissue perfusion is severely compromised. "The agrin/Lrp4/MuSK signaling pathway is essential for survival as mice deficient for either agrin, Lrp4, MuSK or Dok-7 die at birth because of respiratory failure." (PMID 24520420, 2014). "The critical role of MuSK signaling is supported by the fact that mice deficient in agrin, Lrp4, MuSK, or Dok-7 lack NMJs and die at birth from respiratory failure." (PMID 23326516, 2013). "MuSK‐Abs were first described in patients with severe generalized symptoms who often presented with bulbar and respiratory failure, but some present first with ocular symptoms only." (PMID 33094484, 2021). "This might be advantageous as loss of genes that are essential for muscle function (such as MuSK) will result in respiratory failure and death of the mice." (PMID 37777530, 2023).
spinal muscular atrophy (4 papers, 2020 to 2024). A motor neuron disease that affect the muscles, and characterized by muscle weakness and atrophy resulting from progressive degeneration and irreversible loss of the anterior horn cells in the spinal cord (i.e., lower motor neurons) and the brain stem nuclei. "Furthermore, administration of a stabilized form (NT-1654) of the C-terminal 44 kDa fragment of motor neuron-derived agrin, a MuSK activator, enhances NMJ formation and improves motor behavior and survival of a mouse model of spinal muscular atrophy." (PMID 32758427, 2020).
COVID-19 (3 papers, 2020 to 2025). A disease caused by infection with severe acute respiratory syndrome coronavirus 2. "Pertinent lab values from admission (CMP, CBC, NT-proBNP, COVID-19/influenza/RSV, TSH/T4/T3, and hepatitis panel) and during hospitalization (aldolase, MuSK antibody, and acetylcholine receptor antibody)." (PMID 40519473, 2025). "Fifteen patients with MG and COVID-19 were identified, including 10 patients with the anti-acetylcholine receptor (AChR) antibody, one patient with the anti-muscle-specific tyrosine kinase (MuSK) antibody, and four patients without serological definition." (PMID 33013676, 2020).
Hashimoto thyroiditis (3 papers, 2024 to 2025). An autoimmune disorder caused by the production of autoantibodies against thyroid tissue. "In a review of 18 cases of new-onset MG following SARS-CoV-2 infection, 2 patients had Hashimoto thyroiditis and 1 patient had Graves disease; 16 were positive for anti-AChR antibodies and 2 for anti-MuSK antibodies." (PMID 39882352, 2025). "Moreover, the greater the diversity of autoantibodies present in MG patients (e.g., concurrent presence of AChR, Titin, and MuSK antibodies), the higher the incidence of thyroid dysfunction, among which Hashimoto’s thyroiditis is the most common and often progresses to hypothyroidism." (PMID 41393996, 2025).
hepatocellular carcinoma (3 papers, 2018 to 2021). A malignant tumor that arises from hepatocytes. "Besides, it has also been observed that agrin is overexpressed and secreted in tumor cells such as hepatocellular carcinoma (HCC), and is responsible for enhancing tumor cell proliferation and migration via the Lrp4/MuSK signaling." (PMID 35174224, 2021).
motor neuron disease (3 papers, 2018 to 2024). "In 5 patients (4 with motor neuron disease and 1 with uncertain diagnosis), the antibody to MuSK was borderline on CBA." (PMID 29518096, 2018). "Antibodies against lipoprotein receptor–related protein 4 (LRP-4) may be found associated with the MuSK or AChR antibodies or in isolation, although they are also present in patients with motor neuron disease and patients without evidence of diseases." (PMID 39105625, 2024).
bipolar disorder (2 papers, 2011 to 2014). A disorder of the brain that causes unusual shifts in mood, energy, activity levels and the ability to carry out day-to-day tasks. "MUSK, which encodes a protein responsible for the assembly of receptors in post-synaptic neuromuscular junctions, was abnormally expressed in samples of bipolar disorder and major depression." (PMID 22373040, 2011). "For example, the ubiquitous protein, UBC, was abnormally expressed in schizophrenia samples and interacted with the maker genes of schizophrenia (i.e. TSC2, SCNN1A and USP2), bipolar disorder (i.e. MUSK), and major depression (i.e. MUSK and FLT3)." (PMID 22373040, 2011). "For example, one study identified a set of disease markers for bipolar disorder that includes SEC24C (involved in vesicular transportation from endoplasmic reticulum to Golgi apparatus) and MUSK (which encodes proteins responsible for receptor assembly in the neuromuscular junction)." (PMID 25202283, 2014).
Escobar Syndrome (2 papers, 2022 to 2023). "While CHRNG mutations caused Escobar syndrome for 75 patients of known cases, a number of patients had a genetic etiology associated with variants in the TPM2, CHRND, CHRNA1, MUSK, MYH3, RAPSN, and DOK7 genes." (PMID 36292632, 2022).